AR (androgen receptor)
Diseases named in the same sentence as AR in open-access papers (continued):
Sharing a sentence is not in itself a finding about the gene and the disease.
prostate carcinoma (continued). "Some of these mechanisms are being targeted in clinical trials; however, none are presently curative and the molecular mechanisms of AR-dependence and the transition to apparent AR-indifference of almost all prostate cancers under APDT pressure are still not understood." (PMID 35328625, 2022). "It should be noted, however, that high AR activity may not be universally sufficient to confer sensitivity of prostate cancer to SPA, as DU145 cells transduced to express high AR remain resistant to growth inhibition by SPA, even with high AR overexpression." (PMID 36194476, 2022). "In AR-negative prostate cancer cells, OCT4 forms LLPS with Nuclear respiratory factor 1 (NRF1)." (PMID 35966880, 2022). "The radioconjugates [111In]In-DOTA-Tz-TCO-PEG4-AR, [111In]In-DOTAGA-Tz-TCO-PEG4-AR, [111In]In-DOTA-Tz-TCO-Pip-AR and [111In]In-DOTAGA-Tz-TCO-Pip-AR were studied to determine their uptake and internalization in a prostate cancer in vitro model using the well-established GRPR-positive cell line, PC3." (PMID 36559063, 2022). "However, prostate cancers often relapse and progress to a stage termed as castration-resistant prostate cancers (CRPC), and the majority of these CRPCs still depend on the AR signaling for growth and progression (the AR addictiveness)." (PMID 35372068, 2022). "In the context of AR-independent prostate cancer, which usually emerges as a result of ARSI therapies, FGF signaling seems to play a pivotal role, where non-neuroendocrine AR-negative tumors rely on FGF and MAPK signaling to bypass AR requirements in prostate cancer." (PMID 35740556, 2022). "Finally, exchange of the VHL binding moiety to a VH101 analogue generated the most potent AR-degrader 80, ARD-69, with sub-nanomolar DC50 values in prostate cancer cell lines and inducing considerable reduction in AR protein levels in xenografted tumour tissue in mice." (PMID 35983982, 2022). "Therefore, CRPC is not an initial clinical presentation of prostate cancer, but the consequence of anti-AR therapies." (PMID 35832549, 2022). "Many studies indicate that androgen-receptor pathway inhibition (ARPI) induces a cascade of changes in DNA structure, gene expression, and selective translation of proteins that regulate signaling networks to provide survival of sub-populations of prostate cancer cells." (PMID 35963852, 2022). "On the other hand, ERβ down-regulates AR in a negative feedback loop in prostate cancer cells." (PMID 35966880, 2022). "To date, no treatments are available for AR-negative prostate cancers." (PMID 34681244, 2021). "This review aims to raise awareness in oncology and urology communities regarding the complexity of bone health, and to provide a framework for management strategies for patients with nonmetastatic castrate-resistant prostate cancer receiving androgen receptor inhibitor treatment." (PMID 33028943, 2021). "AR gene amplifications, which have been detected in up to 60% of pretreated CRPC patients, are also responsible for tumor progression despite optimal ADT; in fact, they determine higher expression of AR in prostate cancer tissue with consequent cell growth despite low androgen levels." (PMID 34638258, 2021). "Through the study of various serotypes, it is found that serotype 12E1A inhibits AR-mediated transcription and prostate cancer cell survival, suggesting that E1A12-targeted AR may have a potential therapeutic effect on the treatment of advanced prostate cancer with increased AR." (PMID 34956913, 2021). "Due to this gain of oncogenic AR function, prostate cancers (PCa) initially are nearly universally responsive to androgen deprivation therapy (ADT), since this induces an autocrine TGFβ-stimulated apoptotic death of such malignant ligand/AR (A+/AR+)-dependent PCa cells." (PMID 34946547, 2021). "Prostate cancer is the most commonly diagnosed non-cutaneous cancer in North American men, driven primarily by AR signaling for growth and survival." (PMID 32946061, 2021).
prostate carcinoma (continued). "Moreover, changes in hypoxia/reoxygenation have previously been found to stimulate androgen receptor trans-activation and sensitization in prostate cancer cells that is independent of HIF-1 signaling." (PMID 34572020, 2021). "Therapies that inhibit androgen receptor signaling induce cell death by apoptosis in prostate epithelium and involution of non-malignant prostate gland, but are not effective against advanced prostate cancer." (PMID 33668112, 2021). "Methods used to assess AR status did not permit to analyze tumor content burden, often providing useful information regarding prediction to therapeutic response and prognosis, mainly in advanced prostate cancer." (PMID 33500577, 2021). "Indeed, AR-negative prostate cancer cells have been shown to respond to AURKA, FGFR, or MAPK inhibitors, in line with the notion that these pathways are activated as a result of the lineage switch." (PMID 33420371, 2021). "In this study, we examined whether and how CAP-activated medium (PAM) delivers selectivity against AR-independent prostate cancers using human normal epithelial prostatic cells PNT1A and AR-negative DU145 prostate cancer cells, respectively." (PMID 34476012, 2021). "To experimentally dissect the role of KIF4A in prostate cancer, we tested whether KIF4A expression was required for prostate cancer cell proliferation and or survival in both AR-dependent (LNCaPi, C42Bi, and 22Rv1i) and AR-independent (PC3i and DU145i) cell-line models." (PMID 34326322, 2021). "While POM121 is highly upregulated in advanced lethal prostate cancer (PC), it is found to promote PC aggressiveness by augmenting the selective importin-dependent nuclear shuttling of oncogenic MYC, E2F1, Androgen receptor (AR), and GATA2 (PC-specific) transcription factors (TFs)." (PMID 34970494, 2021). "In addition, miR-130a acts as a tumor suppressor in prostate cancer and triple-negative breast cancer, inhibiting androgen receptor (AR) and mitogen-activated protein kinase (MAPK) pathways and targeting foS-like antigen 1 (FOSL1)." (PMID 35187064, 2021). "There is interest in Pin1 as a potential prognostic marker for prostate cancer, but there are no reports on whether Pin1 expression in prostate cancer influences AR signaling." (PMID 33753863, 2021). "Collectively, these findings suggest that targeting the AR NTD with ATRA and ralaniten may induce G1 arrest and senescence in prostate cancer cells that express AR-Vs, by a mechanism involving the Skp2/p27Kip1 pathway and Rb inactivation but not requiring p16INK4A." (PMID 33753863, 2021). "Besides, it was reported that MID1 could act as a translational inducer of AR protein, which in turn decreased MID1 levels in response to androgen stimulation in prostate cancer." (PMID 35004288, 2021). "Given the critical importance of AR transcriptional control in various diseases such as androgen insensitivity syndrome, benign prostatic hyperplasia, and prostate cancer, intriguingly, this isoform may potentially be a target for therapy not only for SBMA but also for other AR-related conditions." (PMID 34417184, 2021). "Importantly, we show in the same setting that inhibition of EZH2 protein substantially blocked the castration-induced polarization change towards M2, uncovering a thus far underappreciated role for EZH2 in macrophage polarization another rationale towards co-targeting AR and EZH2 in prostate cancer." (PMID 34857732, 2021). "This work further suggests that AR-negative prostate cancers may depend on FGFR for oncogenic cell growth." (PMID 33456711, 2021).
prostate carcinoma (continued). "Moreover, AR and PTEN pathways are regulated by reciprocal feedback, further supporting the relevance of the PTEN-PI3K-AKT pathway disruption in the development of prostate cancer." (PMID 34638258, 2021). "The classification of AR-negative prostate cancers remains thus a major challenge in the field." (PMID 33420371, 2021). "Since the proliferation and survival of prostate cancer heavily depend on AR even in the absence of androgen, we asked whether IRE1α expression has effects on AR activation." (PMID 34295814, 2021). "Thus, understanding the occurrence of AR-negative prostate cancer has become an important and urgent clinical need in the field." (PMID 33420371, 2021). "In this study we used two prostate cancer cell lines, DU145 and 22Rv1, that are respectively androgen receptor (AR) negative and positive, a receptor whose function is critical for prostate cancer progression and with which there is known cross-talk with the IGF-axis." (PMID 33969359, 2021). "PMEPA1 is a multifunctional protein and has a growth-promoting or inhibitory role in prostate cancer, depending on whether the cancer cells are negative or positive to AR." (PMID 34777336, 2021). "We used PC3 cells to detect the effect of ACSS3 in AR negative prostate cancer, and the results showed that ACSS3 could also inhibit the proliferation of PC3 cells." (PMID 33391508, 2021). "Using scWGS, androgen receptor (AR) gene positive or negative prostate cancer CTC subpopulations were identified during the period of androgen deprivation therapy (ADT); CNV evolution reflecting clinical response and disease progression was also observed in CTCs." (PMID 33802312, 2021). "It is, however, anticipated that this effect could be observed only in menin-expressing TNBC as it has been described for castration-resistant prostate cancer cell lines that do not express an androgen receptor such as PC-3 (C.Cherif, Oncogene, in revision)." (PMID 34356858, 2021). "Moreover, combination effects of mTOR inhibitors and HDAC inhibition were seen independent of the AR status, thus potentially offering an opportunity for hard-to-treat, castration-resistant prostate cancer." (PMID 33562653, 2021). "Next, to identify kinases of which knock‐down enhanced the docetaxel sensitivity in PCa cells, we conducted a high‐throughput kinome‐wide shRNA screen in the AR‐negative DU145 prostate cancer cells in the presence or absence of a sublethal concentration of docetaxel." (PMID 34322995, 2021). "In support of this, our data in vitro and in vivo data demonstrated that KIF4A promotes phenotypes associated with poor prognosis in mCRPC, irrespective of AR status, suggesting KIF4A is a driver gene that promotes disease progression in human prostate cancers." (PMID 34326322, 2021). "KIF4A and WDR62 drive aggressive prostate cancer phenotypes irrespective of AR-status." (PMID 34884583, 2021). "In hormone-dependent cancers such as breast or prostate cancer, early evidence suggested that HDAC inhibition affects the expression of hormone receptors such as the estrogen receptor (ERα, ERβ) and the progesterone receptor (PR), as well as the androgen receptor (AR)." (PMID 33562653, 2021). "As reported, LNCaP, C4-2, 22RV1, and VCaP cells exhibited robust AR activity by means of KLK3 expression, whereas PC3 and DU145 (AR-negative prostate cancer cells) or RWPE1, PWR1E, and BPH1 cells (benign prostate immortalized cells) exhibited low activity of the nuclear receptor." (PMID 34503116, 2021). "PMEPA1 has a growth-promoting or inhibitory role in prostate cancer, depending on whether the cancer cells are negative or positive to androgen receptor (AR)." (PMID 34777336, 2021). "Panels 5, 6, lanes 2–8); this suggests that the AR-positive LNCaP spheroids may not depend on FGFR signaling as much as AR-negative prostate cancer cells." (PMID 33456711, 2021).
prostate carcinoma (continued). "However, derivation of enzalutamide-resistant cells from four different prostate cancer cell lines (including LNCaP but not LNCaP/AR) was unable to replicate the SOX2-based mechanism." (PMID 33477370, 2021). "Consequently, whilst enzymes in the hexosamine biosynthesis pathway are AR dependent, and many are overexpressed in prostate cancer, there is not necessarily a direct relationship between their activity and the OGlcNAcylation status of OGT substrates." (PMID 34660272, 2021). "Interestingly, TMPRSS2 has been widely studied in the context of prostate cancer, where it is highly expressed, and TMPRSS2 expression is increased in response to androgens through direct transcriptional regulation by the androgen receptor (AR)." (PMID 33310900, 2020). "Whereas clinical trials for the treatment of prostate cancer with orteronel were terminated in phase III because of a lack of significant effect on OS, it is currently being investigated in a phase II clinical study of women with AR-positive metastatic TNBC (NCT01990209)." (PMID 33138097, 2020). "Taken together, our study provided new insights into the modulations of AR and TGF-β signaling through understudied isoforms (d and e) of PMEPA1 gene, providing the new understandings of gene networks centering AR/TGF-β signaling regulation in the context of prostate cancer." (PMID 32064040, 2020). "Interestingly, we discovered that JQ1 has different effects on cell migration in AR-positive and AR-negative prostate cancer cells, which indicates that the function of BRD4 is cellular-context dependent." (PMID 33343366, 2020). "However, suppressing AR with siRNA in prostate cells increased macrophage recruitment via CCL2 upregulation, which might promote prostate cancer." (PMID 32849595, 2020). "AR-expressing prostate cancer cell lines, LNCaP, VCaP, C4-2, and 22RV1, non-AR expressing PC3 tumor cells, and non-tumorigenic RWPE-1 prostate epithelial cells were treated with varying concentrations of GSA0932 for 48 hours, and proliferation evaluated using the MTT assay." (PMID 32477465, 2020). "Given the reduced AR protein expression in sarcomatoid tumors and that the castrate DKO mice all had sarcomatoid pathology, it is likely that the rapid onset of castrate-resistant tumor growth was due to the progression of the prostate cancer to a sarcomatoid pathology." (PMID 32986721, 2020). "As for NONO functions in prostate cancer, it is indicated that NONO promotes the proliferation of prostate cancer cells and controls the splicing regulation, which upregulates the expression of mRNAs encoding the full-length AR and AR-V7 proteins in CRPC." (PMID 32106418, 2020). "In early FDHT-PET imaging studies, a circulating lipophilic but somewhat more polar radiolabeled metabolite was noted, and although it did not bind to AR and was not taken up by prostate cancer lesions, it made accurate measurement of blood levels of FDHT for pharmacokinetic modeling more difficult." (PMID 32718075, 2020). "As a major cholesterol metabolite, 27HC has attracted the attention of prostate cancer investigators over the past decade, and it was demonstrated to stimulate the proliferation of RWPE-1 normal prostate epithelial cells in an ER- and androgen receptor (AR)-dependent manner." (PMID 32650428, 2020). "Furthermore, 27HC induced AR transcriptional activity and expression of AR-target genes in RWPE-1 cells, and as 27HC does not directly bind to AR, it is possible that there is potential crosstalk between ER and AR in the presence of 27HC in prostate cancer." (PMID 32650428, 2020). "In prostate cancer, in addition to the known role of miR-373 in inducing mesenchymal-epithelial transition, another microRNA miR-371a-3p, which belongs to the same family and contains the AAGUGC sequence at position 1–6, is known to down-regulate the androgen receptor." (PMID 32231998, 2020).
prostate carcinoma (continued). "Nevertheless, it should be noted that the growth-inhibitory effects of MF-15 were not restricted to AR-positive prostate cancer cells, since also AR-negative PC-3 cells were affected by MF-15 in our study, exerting a similar effect as the chemotherapeutic drug docetaxel." (PMID 32731472, 2020). "Moreover, AR is known to be crucial for the development of prostate cancer, but we did not detect any correlation between AR and PD-L1 in prostate cancer." (PMID 32579541, 2020). "Because normal prostate tissues rely on androgen and its receptor, androgen receptor (AR), for development and maintenance of homeostasis, targeting the AR pathway via androgen deprivation therapy (ADT) constituted a viable mechanism that was generally utilized for treatment of prostate cancer." (PMID 32585812, 2020). "While our screens are target-agnostic, and were not explicitly aimed at looking at the role of the androgen receptor, they are complementary to previous screens, and in combination with them, provide valuable insights into the functional role of microRNAs in prostate cancer." (PMID 32231998, 2020). "Interestingly, for all the three independent datasets analyzed, an enrichment of up- and down-regulated transcriptional targets for both AR and ESR1 emerged, suggesting a possible interplay between these two proteins in controlling the neuroendocrine transdifferentiation process of prostate cancer." (PMID 32041153, 2020). "The androgen receptor (AR) signalling pathway is critical for the growth and survival of prostate cancer cells, including those of lethal castration‐resistant prostate cancer (CRPC), demonstrating that AR is a valid therapeutic target for treating prostate cancer." (PMID 32459381, 2020). "Of note, PMEPA1-c had no impacts on the growth of prostate cancer cells and AR or TGF-β signaling." (PMID 32064040, 2020). "Together, these results suggest that ERRα overexpression could enhance in vitro resistance to androgen deprivation and antiandrogen in AR-positive but not AR-negative prostate cancer cells." (PMID 32226548, 2020). "Intriguingly, we also observed that knockdown of HNF4α could enhance the expression of AR and its variant AR45, and functionally promote the resistance to androgen-deprivation in vitro and in vivo in LNCaP prostate cancer cells (data not shown)." (PMID 31695151, 2020). "In addition to underpinning resistance to AR-targeted therapy, induction of CXCL8 signalling modulates the sensitivity of prostate cancer cells to several novel molecular targeted therapies and chemotherapeutic agents, including oxaliplatin that induces DNA double-strand breaks in CaP cells." (PMID 32743555, 2020). "About 50–70% of prostate carcinomas harbor common chromosomal rearrangements fusing one of the ETS transcription family genes (ERG, ETV1, ETV4 or FLI1) with androgen-regulated genes, most commonly TMPRSS2, leading to disruption of androgen receptor signaling via activation of EZH253." (PMID 32873863, 2020). "Likewise, neither of the 2 commonly studied AR-regulated prostate cancer cell lines (LNCaP and VCaP) harbored a low AR-MethSig median methylation ratio." (PMID 32149736, 2020). "However, in androgen refractory prostate cancer cells, regardless of the presence of androgen, the AR is nuclear localized." (PMID 32256979, 2020). "Finally, because of the high expression of AR in CTCs from TNBC patients, we explored the effect of pharmacological inhibition of the AR pathway, which is a common therapeutic strategy in AR-dependent tumors such as prostate cancer." (PMID 32012729, 2020). "Moreover, several studies provided evidence that AR signaling links to the DDR in prostate cancer cells, which may have relevance for the first line disease management using ADT and AR-targeted agents." (PMID 31197228, 2020).